APP (amyloid beta precursor protein)
Diseases named in the same sentence as APP in open-access papers (continued):
Sharing a sentence is not in itself a finding about the gene and the disease.
Cognitive impairment (continued). "Our data document clear age-dependent cognitive deficits in the APP/PS1 KI mice in both recognition memory (NOR) and spatial reference memory (RAWM) that become more prominent with increasing age." (PMID 23705774, 2013). "We chose to use PS1-KI animals as control group as these mice overexpress mutant Presenilin-1 gene (M146V substitution) but, by lacking the expression of mutant APP and h-tau, do not show Aβ or tau-dependent pathology nor AD-related cognitive deficits." (PMID 21423579, 2011). "Both genetic knockdown and pharmacological inhibition of ELK1 reduce APP amyloidogenic processing by promoting the SYVN1-mediated ubiquitination and degradation of PS1, thereby inhibiting Aβ generation and alleviating synaptic and cognitive impairments in a mouse model of AD." (PMID 40307574, 2025). "According to these findings, we hypothesize that the BDNF produced by hUC-MSCs may enhance the survival of neural stem/progenitor cells in the subgranular zone of the dentate gyrus and improve astrocytes in the APP/PS1 hippocampus, thereby indirectly mitigating inflammation and cognitive deficits." (PMID 40564462, 2025). "We found that APP protein was highly expressed in the brains of APP/PS1 mice at an early stage, which may explain the mild cognitive impairment seen in the young APP/PS1 mice during the early stage of AD in the absence of substantial Aβ plaque accumulation." (PMID 38606360, 2024). "At 12 M, minor cognitive impairments could be detected in APP+/− rats but not in R995-hTau+/− and APPxhTau rats." (PMID 39707506, 2024). "Second, even though we only included human subjects with proven APP or PSEN1 mutations and no cognitive impairment, subjects may have been in different pre-symptomatic stages of the disease." (PMID 37608393, 2023). "Further, they found that the APP and SAA double transgenic mice presented relatively intense apoptosis and immune responses in the brain, concluding that SAA enhanced the neuroinflammation in Aβ abundant condition and induced severe cognitive deficits compared with the single transgene of APP." (PMID 38115100, 2023). "In total, 1330 patients with AD or mild cognitive impairment in 404 pedigrees were enrolled; among them, 13.12% of pedigrees carried PSEN/APP missense mutations, 3.71% carried PSEN/APP synonymous/untranslated region variants, and 83.17% did not carry such mutations or variants." (PMID 37365538, 2023). "Taken together, these results indicate that general cognitive deficits manifest in the late stage of the APP/PS1 mice, and that social memory impairment is also observed prior to the appearance of general cognitive dysfunction in the early stages of the APP/PS1 mice." (PMID 35154497, 2022). "In samples from APP/PS1 double-transgenic mice, mild cognitive impairment (MCI) and dementia of Alzheimer-type (DAT) patients, this study found that miR-193b overexpression could repress the mRNA and APP protein expression that would influence Aβ generation in brain." (PMID 36438184, 2022). "Histamine and methylhistamine were significantly elevated in APP/PS1 mice, and previous evidence suggested that neurotransmitter systems including neuronal histamine could contribute to the development and maintenance of AD-related cognitive deficits." (PMID 36618950, 2022). "APP/PS1 mice had been reported to exhibit cognitive impairment at six months of age; thus, we further explored whether OCYYoung‐EVs were able to reverse cognitive impairment and Aβ pathology." (PMID 35508803, 2022). "Thus, in mutant mice overexpressing the amyloid precursor protein (APP), an increase in the activity of PTP1B tyrosine phosphatase was found, which correlates with the development of neuroinflammation and the progression of cognitive deficit." (PMID 36233148, 2022).
Cognitive impairment (continued). "In 2-month-old amyloid precursor protein knock-in (APP-KI) mice, the Clock/Bmal1-driven negative feedback loop of transcription in microglia was impaired, and activation of Rev-erbα promoted the expression of inflammatory cytokines and cognitive impairment." (PMID 35668454, 2022). "In the present article, CIG showed better effects on APP nonamyloidogenic processing, synaptic plasticity, and necroptosis at earlier stages, which may explain the effects of earlier intervention on cognitive impairments." (PMID 34475966, 2021). "Evidence from matched case-control study and APP/PS1 transgenic mice research revealed that increased flux of 27-OHC to the brain could enhance the accumulation and deposition of Aβ, ultimately accelerating cognitive deficits in AD." (PMID 35087849, 2021). "It has been shown that crossbreeding of these mice with APP overexpressing mice resulted in the accelerated accumulation of Aβ accumulation, which was concomitant with increased tau pathology and cognitive impairment, two features usually lacking in APP transgenic mice." (PMID 34452054, 2021). "In this study, the APP/PSI transgenic mice model that is well acknowledged for mimicking the pathological processes of AD is utilized, which presented features of behavioral dysfunction, cognitive disorder, senile plaques, neurofibrillary tangles, and neuronic death." (PMID 33532488, 2021). "In our experiment, to assess whether TBI can aggravate cognitive impairment in the APP/PS1 mouse model, the NOR and OPR tests were performed to evaluate perirhinal cortex- and hippocampal-dependent learning and memory, respectively." (PMID 34539542, 2021). "Therefore, we hypothesized that 1070-nm light could modulate glial cells to promote the clearance of Aβ burden in the brains of APP/PS1 mice, leading to improvements in memory and cognitive deficits." (PMID 34493703, 2021). "Similarly, in APP-KI mice subcutaneous or intravenous injection of human antibody #129 recovered MARCKS phosphorylation at Ser46, decrease of dendritic spines, cognitive impairment, and extracellular Aβ aggregates." (PMID 34635772, 2021). "In the final probe test, FGF21 administration increased the residence time in the target quadrant and the number of crossing the original location of the platform in the APP/PS1 model, suggesting that FGF21 could alleviate cognitive impairment by directly acting on the central nervous system." (PMID 32724479, 2020). "Therefore, intravenous injection appeared to not be sufficient to improve cognitive impairment in APP/PS1 mice." (PMID 32612165, 2020). "Altogether, our results suggest that early multiple IIV immunizations exert a beneficial immunomodulatory effect in APP/PS1 mice by breaking Treg-mediated systemic immune tolerance, maintaining the activation of microglia and removing of Aβ plaques, eventually improving cognitive deficits." (PMID 32075657, 2020). "Thus, we chose to use 8-month-old APP/PS1 transgenic mice without a cognitive impairment or mild cognitive dysfunction to study the preclinical and early stages of AD." (PMID 33519426, 2020). "If dysregulation of APP’s contribution to Fe homeostasis plays a role in AD, that role would be in earlier stages of the disorder, such as mild cognitive impairment (MCI) and Braak stage I, and may not be reflected in the “accumulative phase” (Braak II +)." (PMID 30470799, 2019). "A study in the APP/PS1 mutant mouse model of Alzheimer’s disease, which expresses the transgenes for both mutant APP and mutant presenilin-1 (PS1), demonstrated that transgenic mice develop significant cognitive impairments in spatial working memory and accumulation of amyloid beta in brain tissue." (PMID 31443476, 2019). "In APP transgenic mice, lack of Abca1 increased Aβ deposition and cognitive deficits." (PMID 28241068, 2017).
Cognitive impairment (continued). "However, APP/PS1 double transgenic mice are among the most successful models, promptly developing memory and cognitive impairments and other relevant pathological process, such as Aβ deposition and a robust neuroinflammatory response toward senile plaques, along with synaptic integrity loss." (PMID 29190943, 2017). "Most significantly, 9-month-old APP/PS1 mice exhibit numerous cerebral cortical microvascular microaneurysms and widespread extravasation of resin casting solution from cerebral capillaries that coexists with cerebral amyloid plaques, CAA and cognitive deficits." (PMID 28741167, 2017). "Furthermore, the number of Aβ plaques in the brain has not been found to correlate with the severity of cognitive impairments in humans or in APP and/or PS transgenic mice." (PMID 27388605, 2016). "These deficits were observed prior to the onset of Aβ deposition (which begins around 6-months of age in these mice), which was not different between APP23 and APP+-ob/ob mice, strongly suggesting that the cognitive impairments were independent of amyloid burden in the brain." (PMID 26340637, 2015). "In the present study, we investigated whether EA treatment could ameliorate cognitive impairment and attenuate Aβ deposits, and the effect of EA treatment on BDNF expression and neurogenesis in the amyloid precursor protein (APP)/presenilin 1 (PS1) double transgenic (Tg) mice." (PMID 24447795, 2014). "Thus, while the Thr668Ala mutation on APP, which does not reduce Aß production, prevents memory deficits of FDDKI mice, the Tyr682Gly mutation, which reduces Aß production, causes cognitive defects on its own." (PMID 23451158, 2013). "As expected Tg APP mice did not distinguish both objects, showing cognitive impairment." (PMID 22248049, 2012). "Furthermore, injection of Gal‐9‐Aβ fibrils into the hippocampus of APP/PS1 mice triggered more severe Aβ deposition, synaptic dysfunction, and cognitive impairment than injection of pure Aβ fibrils, indicating that Gal‐9‐seeded Aβ may represent a novel Aβ strain." (PMID 39485716, 2025). "Cognitive impairment was found in MI rats, along with dendritic spine loss, blood-brain barrier (BBB) breakdown, brain mitochondrial dysfunction, and decreased mitochondrial and increased glycolysis metabolism, without the alteration of APP, BACE-1, Tau and p-Tau proteins." (PMID 38362882, 2024). "Therefore, we hypothesized that exercise activated the PI3K/Akt signaling pathway in the hippocampus of APP/PS1 mice, decreased the expression level of BACE1 and correspondingly increased the level of UCHL-1, thereby improving cognitive impairment in the AD state." (PMID 36195875, 2022). "Finally, to confirm whether the expression of these molecules is indeed affected in AD, we also carried out qPCR and western blot analysis on 7‐8‐month‐old APP/PS1 model mice of AD, which is very popular in AD research and exhibits obvious cognitive impairment at 7–8 months of age." (PMID 36401602, 2022). "Here, we decided to challenge the efficiency of RD2 by orally treating old-aged APP/PS1 mice with full-blown pathology over 12 weeks, as this may mimic the patients’ situation more closely at moderate and more advanced disease stages, in respect to plaque pathology and cognitive deficits." (PMID 30003517, 2019). "However, drugs used for the treatment of epilepsy may not reverse cognitive deficits in APP/PS1 models of transgenic mice." (PMID 31248209, 2019). "Electro-acupuncture at DU20 could markedly ameliorate cognitive impairments, reduce aberrant overexpression of β-amyloid, and inhibit neuronal apoptosis, significantly enhance expression levels of mature brain-derived neurotrophic factor (BDNF) and pro-BDNF in APP/PS1 mice." (PMID 29284465, 2017).
Cognitive impairment (continued). "The downregulation of miR-1251-5p and miR-34a-5p might alleviate cognitive deficit by increasing the activity of disintegrin and metalloprotease 10 (ADAM10), a major α-secretase in brain that is capable of attenuating the production of Aβ by cleavage of APP, resulting in soluble APPα." (PMID 29057267, 2017). "Thus, we hypothesized that PM2.5 aspiration might promote BACE1- and γ-secretase- but not α-secretase-mediated cleavage of APP, leading to Aβ synthesis and accumulation and synaptic and cognitive impairment." (PMID 28851397, 2017). "At this time point, APP/PS1 model has just begun to show amyloid plaque deposition, but cognitive impairment has not yet occurred, representing the early stage of AD." (PMID 39415847, 2024). "The current study was part of a larger study to evaluate cognitive deficits in APP/PS1 mice in which Tg mice showed extensive brain amyloid beta concentration, but did not exhibit cognitive deficits through ∼71 weeks of age." (PMID 37250187, 2023). "Here, we assessed the effects of ELS on APP/PS1 mice at 3 months of age, an age at which generally no Aβ pathology or cognitive impairments occur in this model yet." (PMID 37980670, 2023). "Nr3c1ki/ki-APP/PS1 mice displayed neuronal defects and cognitive impairment earlier than controls while non-neuronal indicators of pathology were unaffected." (PMID 35733193, 2022). "Given the marked phenotype differences in APP/PS1 mice with and without partial eNOS deficiency at 8 months of age, future research is required to determine whether partial eNOS deficiency alters the onset of cognitive deficits or Aβ deposition in the brain in APP/PS1 mice." (PMID 35806318, 2022). "APP/PS1 transgenic mice, which express mutant APP and PS1, harbor few Aβ plaques, and show no signs of cognitive deficits at 3.5 months of age." (PMID 33776747, 2021). "It was found that in 10‐month‐old female APP/PS1 mice, compared with the noncerebral vasculature targeting formulation RL, RAP‐RL more efficiently rescued the cognitive deficits of AD model mice at a very low dose (0.34 mg kg−1 DMPC)." (PMID 33511002, 2021). "Importantly, the role of the anti-inflammatory cytokine IL-10 in AD brain remains controversial, since recent studies in APP mice suggested that it may inhibit microglial Aβ clearance, promoting Aβ plaque generation and cognitive impairment (rather than delaying AD progression)." (PMID 32143329, 2020). "It was clearly shown that the improvement of Cef on cognitive impairment of APP/PS1 mice was inhibited after GLT-1 knockdown, i.e., the administration of Cef had no significant improvement on the cognitive impairment in GLT-1±APP/PS1 mice." (PMID 33132901, 2020). "For cytokines contributing to cognitive impairment, chemotactic factor MCP-1, MIP-1β, RANTES and eotaxin only decide deterioration of cognitive performance in SAMP8, not APP/PS1 mice." (PMID 27049828, 2016). "Furthermore, the Aqp4 knockout APP/PS1 mice had more severe deficits in glymphatic transport functions, Aβ plaque deposition, and cognitive impairment, which were not alleviated after the exercise intervention." (PMID 38430054, 2024). "The pyramidal cell layer (PCL) and the stratum radiatum (SR) of the CA1 region and granular cell layer (GCL) of the dentate gyrus (DG) were systematically evaluated firstly in 3-month-old mice, an age when APP/PS1 mice present minimal or no amyloid plaques and cognitive impairment." (PMID 36902054, 2023). "Hereby, we study for the first time, using behavioural, transcriptomic and bioinformatic approaches, depressive-like symptoms in an AD mouse model (APP/PSEN1-Tg mice) at ages before the neuropathological features are manifest and when cognitive impairment is not yet evident." (PMID 33795014, 2021).
Cognitive impairment (continued). "Although we did verify the presence of ES-induced cognitive impairment in young adulthood, we observed no changes after ES in the cognitive measures and parameters of the AHN process in the middle-aged (8–10 months) WT and APP/PS1 mice." (PMID 29563870, 2018). "The 3xTg-AD-H mice exhibit mainly intracellular Aβ accumulation before 12 months of age, accompanied by increased levels of intracellular APP sub-products, as well as Tau pathologies such as intracellular NFT and cognitive impairment, accompanied by astrocytosis but not microgliosis 9,17,34,35." (PMID 29259249, 2017). "Previous studies have shown that APP mice can exhibit seizures; our findings in FAD + rats extend this work by suggesting that high-frequency oscillations and epileptiform activity—even in the absence of overt seizures—may contribute to cognitive impairment." (PMID 40890882, 2025).
cognitive decline (379 papers, 2008 to 2026). "On the flip side, deficiencies and/or loss of leptin are reported to exacerbate cognitive decline in AD, as cognitive function is reportedly much poorer in double-mutant (APP(+)-ob/ob) mice compared to APP(+) mice." (PMID 41462981, 2025). "Crucially, the formulation also modulates key biomarkers associated with cognitive decline, reducing APP and phosphorylated tau levels (about 98% and 1.6-fold vs. H2O2) while increasing Sirtuin 1 and Nrf2 expression (about 3.6-fold and 3-fold vs. H2O2)." (PMID 40807615, 2025). "Correspondingly, APP/PS1-mice show a selective loss of GluA3 at an age coinciding with the initial stages of cognitive decline." (PMID 39779375, 2025). "Abnormal processing of APP membrane proteins produces Aβ amyloid plaques, causing nerve damage and cognitive decline." (PMID 40764944, 2025). "Remarkably, individuals with DS are more susceptible to developing early-onset AD later in life, although the principal cause of cognitive decline in AD is the overexpression of amyloid precursor protein (APP)." (PMID 40385132, 2025). "Within established APP KI models, there is considerable variability in the age of cognitive decline depending on the presence of specific FAD mutations." (PMID 39920176, 2025). "The double-transgenic APP/PS1 mice with mutations associated with familial AD manifest cognitive decline and impaired memory, resembling neuropathological indicators of familial AD." (PMID 39546459, 2024). "Their data also demonstrated that zinc deficiency accelerated cognitive decline by potentiation of NLRP3-dependent inflammation in an APP/PS1 mouse model of AD." (PMID 38648940, 2024). "Specifically, higher APP predicted protein explained 18.9% of faster cognitive decline, whereas APP mRNA levels showed weak and even reversed association." (PMID 35115553, 2022). "Missense mutation of APP gene changes A β Metabolize and regulate A β And cause A β Cognitive decline." (PMID 36620771, 2022). "This enhancement augments APP amyloidogenic processing, leading to Aβ plaque formation and resulting in AD-associated impairments, such as focal neurodegeneration and cognitive decline." (PMID 34063708, 2021). "We demonstrated that the cognitive decline induced by zinc deficiency was completely abated in the APP/PS1 mice deficient in NLRP3." (PMID 33597269, 2021). "APP/PS1 mice deficient in NLRP3 were protected against the accelerated cognitive decline with zinc deficiency." (PMID 33597269, 2021). "In conclusion, these results confirm that enhanced immune suppression caused by ATRA prevents the IIV-induced protection against cognitive decline in APP/PS1 mice." (PMID 32075657, 2020). "Pericyte loss accelerates Aβ pathology and induces tau pathology and cognitive decline in human APP mice." (PMID 33380345, 2020). "The Appp rats add a complementary approach aimed to determine the mechanisms by which the protective APP variant prevents age-associated cognitive decline and AD." (PMID 32022689, 2020). "Neuronal degeneration and loss are regarded as the main contributors to the cognitive decline in AD patients and APP/PS1 mice." (PMID 30871577, 2019). "MT5-MMP emerges as a new pro-amyloidogenic regulator of APP metabolism, whose deficiency alleviates amyloid pathology, neuroinflammation and cognitive decline." (PMID 26202697, 2016). "In summary, the present study demonstrated that Pdx1+/−/APP/PS1 mice exhibit enhanced cognitive decline, Aβ plaque deposition, tau hyperphosphorylation, the loss of synaptic spine protein, and activation of microglia and astrocytes." (PMID 27406855, 2016). "A recently described APP mutation in position 673 (A673T) has been shown to protect against AD as well as against cognitive decline in the elderly independently of AD." (PMID 26895626, 2016).